GADD45A (growth arrest and DNA damage inducible alpha)
Diseases named in the same sentence as GADD45A in open-access papers (continued):
Sharing a sentence is not in itself a finding about the gene and the disease.
acute lymphoblastic leukemia (2 papers, 2009 to 2025). Leukemia with an acute onset, characterized by the presence of lymphoblasts in the bone marrow and the peripheral blood. "To confirm the pivotal role of GADD45A in PTPN21-mediated antiapoptotic effects in acute lymphoblastic leukemia (ALL) cells, we restored the expression of GADD45A through lentiviral transfection, while cells transfected with the pHIV7-SFFV-GFP vector served as a control." (PMID 40305474, 2025).
acute promyelocytic leukemia (2 papers, 2013 to 2024). An aggressive form of acute myeloid leukemia (AML), characterized by arrest of leukocyte differentiation at the promyelocyte stage, due to a specific chromosomal translocation t(15;17) in myeloid cells. "Analysis of promoter status of cell cycle-related genes in the acute promyelocytic leukemia cell line NB4 found that several genes, including GADD45A, were methylated and could be demethylated by the hypomethylating agent arsenic trioxide." (PMID 39728572, 2024).
Alzheimer disease (2 papers, 2024). A progressive, neurodegenerative disease characterized by loss of function and death of nerve cells in several areas of the brain leading to loss of cognitive function such as memory and language. "Here, we analyzed if the deletion of Gadd45a activates pathways involved in neurodegenerative disorders such as Alzheimer’s Disease (AD)." (PMID 38473843, 2024).
atherosclerosis (2 papers, 2017 to 2018). A disease characterized by the build-up of fatty material and calcium deposition in the arterial wall resulting in partial or complete occlusion of the arterial lumen. "Based on these results, one might speculate that increased GADD45A expression might play a role in the accelerated atherosclerosis of patients with RA." (PMID 30138371, 2018). "Thus, further studies are necessary to elucidate the role of GADD45A in atherosclerosis and premature atherosclerosis in RA." (PMID 30138371, 2018). "Further studies are needed to elucidate if and how GADD45A, NCOR1 and PON2 are involved in the development of accelerated atherosclerosis in RA." (PMID 30138371, 2018).
Atrophy (2 papers, 2015 to 2021). Any weakening or degeneration, especially through lack of use. "GADD45A and CDKN1A have previously been identified in several conditions associated with muscle atrophy." (PMID 25567521, 2015). "Based on earlier studies suggesting that viral overexpression of GADD45A is sufficient to induce muscle atrophy, we obtained a conventional genetic knockout mouse model of Gadd45a to evaluate whether preventing Gadd45a induction can ameliorate neurogenic atrophy." (PMID 34128833, 2021).
breast tumor (2 papers, 2013 to 2015). "High levels of strong cytoplasmic staining of Gadd45a were present in areas containing cancer cells of the primary breast tumors." (PMID 23706118, 2013). "In murine models, Gadd45a functions to either promote or suppress breast tumor development via engagement of different signaling pathways depending on the molecular nature of the activated oncogene." (PMID 23706118, 2013).
cholestasis (2 papers, 2016 to 2024). Impairment of the bile flow caused by obstruction within the liver, or outside the liver in the bile duct system. "Particularly, a down-regulation of Car3 and up-regulation of Gadd45a and Nqo1 is indicative of hepatotoxicity, whereas dysregulation of Abcc3 can indicate cholestasis." (PMID 27598887, 2016).
chronic myelocytic leukemia (2 papers, 2017 to 2021). "Finally, Gadd45a is downregulated in a variety of malignancies, including chronic myelocytic leukemia." (PMID 34128833, 2021).
Cognitive impairment (2 papers, 2024). Abnormal cognition is characterized by deficits in thinking, reasoning, or remembering. "In conclusion, deletion of Gadd45a promotes cognitive impairment and exacerbates AD hallmarks, deregulating several biological processes that are proper to the disease: memory impairment, neuroinflammation, synaptic plasticity, and autophagy alterations." (PMID 38473843, 2024). "This suggests that the lack of Gadd45a gene expression exacerbates neuroinflammation and partially explains the cognitive impairment previously observed in this mice model." (PMID 38473843, 2024).
colitis (2 papers, 2014 to 2018). Inflammation of the colon. "A 16-gene signature (CARD12, CCL3, CCR3, CXCL1, F5, FAM210B, GADD45A, IL18bp, IL2RA, IL5, IL8, MMP9, PTGS2, SOCS3, TLR9 and UBE2C) was identified from 30 days post-tremelimumab initiation blood that discriminated patients developing grade 0–1 from grade 2–4 diarrhea/colitis." (PMID 30227886, 2018).
cyst (2 papers, 2017 to 2021). A sac-like closed membranous structure that may be empty or contain fluid or amorphous material. "This was supported by an induction of caspase-3 and gadd45a expression in the cyst and a downregulation of BCL-2 and BAX in the adjacent lung tissues." (PMID 35274045, 2021). "On this basis, we speculated that 45 Gy might be a safe and effective dose for treating pulmonary hydatidosis in sheep, which induced lower expression of caspase-3 and gadd45a in the cyst and a downregulation of BCL-2 and BAX in the adjacent lung tissues." (PMID 35274045, 2021).
diabetic kidney disease (2 papers, 2023 to 2026). Progressive kidney disorder caused by vascular damage to the glomerular capillaries, in patients with diabetes mellitus. "Similar to GADD45A, GADD45B expression was increased in various glomerular diseases, such as IgA nephropathy and diabetic kidney disease." (PMID 37511062, 2023). "DDIT3, GADD45A, THBS2, CCL2, and CSF1R showed consistent expression trends across platforms, and are known mediators of inflammation, extracellular matrix remodeling, and stress responses in diabetic kidney disease." (PMID 41481573, 2026).
Hodgkins lymphoma (2 papers, 2015 to 2024). A heterogeneous group of malignant lymphoid neoplasms of B-cell origin characterized histologically by the presence of Hodgkin and Reed-Sternberg (HRS) cells in the vast majority of cases. "Additionally, in classical Hodgkin lymphoma cell lines, the antitumor effect of the demethylating agent decitabine was associated with induction of genes that negatively regulate cell cycle progression, including GADD45A." (PMID 39728572, 2024). "Also included was GADD45A, a growth arrest and DNA repair gene previously shown to be a KLF4-inducible gene in Hodgkin lymphoma cells and a stimulator of autophagy during skeletal muscle atrophy." (PMID 26109433, 2015).
injury (2 papers, 2014 to 2021). Damage inflicted on the body as the direct or indirect result of an external force, with or without disruption of structural continuity. "Beyond the neuromuscular system, GADD45A has also been shown to have a protective role in mouse models of ventilator-induced lung injury as well as radiation- and bleomycin-induced lung injury." (PMID 34128833, 2021).
ischemia (2 papers, 2017 to 2021). A hypoperfusion of the BLOOD through an organ or tissue caused by a PATHOLOGIC CONSTRICTION or obstruction of its BLOOD VESSELS, or an absence of BLOOD CIRCULATION. "Gadd45a induction has also been observed in several models of neuronal injury, including ischemia, spinal cord transection, and sciatic nerve crush, and findings from all of these studies suggest that its upregulation has a protective role after neuronal insult." (PMID 34128833, 2021).
lung adenoma (2 papers, 2007 to 2017). A benign, well circumscribed epithelial neoplasm that arises from the bronchus or the lung parenchyma. "A recent animal study had shown that 100% of XPC-deficient mice develop spontaneous lung tumors, the majority of which were adenomas; furthermore, when the mice had XPC and Gadd45a deleted at the same time, their lung adenomas were progressing to non-small cell lung adenocarcinomas." (PMID 17498315, 2007).
lymph node metastasis (2 papers, 2012 to 2016). "The presence of lymph node metastasis, and poor differentiation were associated with mRNA expression levels of GADD45a in ESCC (P = 0.007, P = 0.006, P = 0.010 and P = 0.005)." (PMID 22313682, 2012).
nonalcoholic steatohepatitis (2 papers, 2021). "Gadd45a-null mice also show more severe fibrosis in a mouse model of nonalcoholic steatohepatitis, a form of hepatic scarring that can lead to liver failure, suggesting a protective role in this condition as well." (PMID 34128833, 2021).
renal carcinoma (2 papers, 2021 to 2022). A carcinoma arising from the epithelium of the renal parenchyma or the renal pelvis. "In 4-hydroxyestradiol stimulated renal cancer cells, COMT caused increased apoptosis along with increased GADD45a levels." (PMID 34587154, 2021).
renal cell carcinoma (2 papers, 2014 to 2023). "Moreover, GADD45A is also involved in many key processes of kidney diseases, such as cell cycle progression in CKD, DNA damage or repair in doxorubicin-induced kidney injury, and resistance to chemotherapy or radiotherapy in renal cell carcinoma cells." (PMID 37511062, 2023).
rhabdomyosarcoma (2 papers, 2008). A rare aggressive malignant mesenchymal neoplasm arising from skeletal muscle. "For rhabdomyosarcoma, increased GADD45A has previously been associated with less aggressive tumor behaviour." (PMID 18959781, 2008). "For rhabdomyosarcoma, increased GADD45A was associated with less aggressive tumor behaviour." (PMID 19077262, 2008).
rheumatoid arthritis (2 papers, 2019 to 2021). A chronic, systemic autoimmune disorder characterized by inflammation in the synovial membranes and articular surfaces. "GADD45a -589CC genotype is associated with protection against rheumatoid arthritis in DR4-negative individuals." (PMID 31195707, 2019). "GADD45a promoter region -589G/G or C/G (rs581000) genotypes could prevent rheumatoid arthritis." (PMID 31195707, 2019).
soft tissue sarcoma (2 papers, 2008). A malignant neoplasm arising from muscle tissue, adipose tissue, blood vessels, fibrous tissue, or other supportive tissues excluding the bones. "In a variety of soft tissue sarcoma cell lines GADD45A was found to increase cell cycle arrest and apoptosis {Zhu, 2008 #165}." (PMID 18959781, 2008).
T cell lymphomas (2 papers, 2014 to 2016). "In line with this, our data showed that deletion of Gadd45a increased the incidence of T-cell lymphoma in ATM−/− mice." (PMID 24474198, 2014).
ZIKV infection (2 papers, 2020 to 2021). "A previous study showed that ZIKV infection dysregulates human neural stem cell growth with upregulated GADD45A and other genes associated with cell cycle arrest." (PMID 32287277, 2020).
acute lung injury (1 paper, 2014). A condition of lung damage that is characterized by bilateral pulmonary infiltrates (pulmonary edema) rich in neutrophils, and in the absence of clinical heart failure. "The regulation of GADD45a expression by mechanical stress and its relationship with acute lung injury (ALI) susceptibility and severity, however, remains unknown." (PMID 24940746, 2014).
adenomyosis (1 paper, 2022). The growth of endometrial tissue inside the muscular wall of the uterine corpus. "Similarly, the PGR-repressed genes Gadd45a, Ets2, Vstm4 and C1qtnf6 may be important genes related to progesterone resistance-mediated mechanisms of adenomyosis development." (PMID 35563206, 2022).
agranulocytosis (1 paper, 2016). "In addition, carriers of GADD45A rs581000C had a lower risk of anemia, while carriers of GADD45B rs2024144T had a significantly higher risk for leukocytopenia or agranulocytosis." (PMID 26993769, 2016).
allergic disease (1 paper, 2021). An immune response that occurs following re-exposure to an innocuous antigen, and that requires the presence of existing antibodies against that antigen. "Children with higher value of Growth Arrest and DNA Damage Inducible-α (GADD45A) as well as the proteases MPO and MMP9 also had higher risk to develop allergy." (PMID 33722194, 2021).
amyotrophic lateral sclerosis (1 paper, 2015). Amyotrophic lateral sclerosis (ALS) is a neurodegenerative disease characterized by progressive muscular paralysis reflecting degeneration of motor neurons in the primary motor cortex, corticospinal tracts, brainstem and spinal cord. "Furthermore, CDKN1A and GADD45A are also related to other muscular disorders such as amyotrophic lateral sclerosis." (PMID 25567521, 2015).
aortic stenosis (1 paper, 2025). Aortic valve stenosis is a aortic valve disease caused by the incomplete opening of the aortic valve. "Clinical data obtained from left ventricular myocardial intraoperative biopsies obtained at surgery showed lower levels of GADD45A expression in patients with aortic stenosis compared to control subjects." (PMID 40301189, 2025).
blast crisis (1 paper, 2017). "Notably, retrospective historical analysis of these patients revealed that all blast crisis patients that exhibited low levels of Gadd45a expression exhibited poor response to all forms of therapy resulting in the demise of most of these patients (data not shown)." (PMID 28086219, 2017).
brain tumor (1 paper, 2025). "On the molecular level, all three cell cycle arrest genes that were upregulated under combination therapy in our study (GADD45A, CDKN1A, and BTG2), where Cx43 function was inhibited, showed a positive correlation with GJA1 levels in brain tumor tissue." (PMID 39680504, 2025).
cardiac hypertrophy (1 paper, 2025). "Deletion of Gadd45a also resulted in substantial cardiac hypertrophy, which negatively impacted cardiac morphology and function in knockout mice." (PMID 40301189, 2025). "In agreement with the metabolic changes depicted above, Gadd45a suppression in mice yielded cardiac hypertrophy, as demonstrated by the increase in the heart weight (HW) to body weight (BW; HW/BW) and HW to tibial length (HW/TL) ratios." (PMID 40301189, 2025). "We next explored the potential mechanism involved in the cardiac hypertrophy arising as a consequence of Gadd45a deletion." (PMID 40301189, 2025). "Finally, apoptosis might be another important contributor to the cardiac hypertrophy observed in Gadd45a KO mice, since excessive apoptosis can lead to a loss of cardiomyocytes, which the heart may try to compensate for by enlarging the remaining cells and, thus, cause cardiac hypertrophy." (PMID 40301189, 2025). "Further studies are warranted to examine the role of GADD45A in stressed conditions, such as in mice subjected to transverse aortic constriction, which will provide valuable information regarding the function of this protein in cardiac hypertrophy." (PMID 40301189, 2025). "In our study, Gadd45a suppression in KO mice resulted in robust cardiac hypertrophy." (PMID 40301189, 2025). "Another limitation of the study is that we have not investigated the effects of GADD45A deletion in female mice, nor the occurrence of gender-differences in the development of cardiac hypertrophy." (PMID 40301189, 2025).
chronic hepatitis b (1 paper, 2023). "This study showed that rs225014 (DIO2), rs532446 (GADD45A), rs12031994 (AKT3), rs11119982 (ATF3), rs10865710 (PPARG) are associated with the increased risk of liver disease progression in chronic hepatitis b carriers." (PMID 37059745, 2023). "As a result, our study demonstrated that rs225014 (DIO2), rs532446 (GADD45A), rs12031994 (AKT3), rs11119982 (ATF3), rs10865710 (PPARG) might contribute to the increased risk of liver disease progression in chronic hepatitis b carriers." (PMID 37059745, 2023).
cutaneous melanoma (1 paper, 2022). A primary melanoma arising from atypical melanocytes in the skin. "Thereby, the increased GADD45A expression observed after the loss of MAGOH/B could be efficiently downregulated in the cutaneous melanoma cell lines Mel Ho and 501Mel." (PMID 36497117, 2022). "This indicates a significant influence of MAGOH and MAGOHB on the expression of the pro-apoptotic NMD target GADD45A in cutaneous malignant melanoma." (PMID 36497117, 2022). "In this study we could identify the NMD target GADD45A as strongly and significantly upregulated in cutaneous melanoma cells after KD of MAGOH and MAGOHB." (PMID 36497117, 2022). "Our study demonstrates that the KD of MAGOH and MAGOHB increased GADD45A expression in cutaneous melanoma, an effect that might be mediated by an impairment of NMD induced by the loss of MAGOH and MAGOHB." (PMID 36497117, 2022). "A KD of MAGOH/MAGOHB and the resulting increase in GADD45A expression in cutaneous melanoma could possibly enhance the effect of other cancer therapies whose main mode of action is not to induce DNA damage, such as targeted therapy or immunotherapy." (PMID 36497117, 2022). "In addition, it was further shown that a simultaneous downregulation of GADD45A together with MAGOH and MAGOHB could attenuate cell death in cutaneous melanoma cells, indicating GADD45A a strong tumor suppressor in cutaneous malignant melanoma." (PMID 36497117, 2022). "After KD of MAGOH and MAGOHB using the siMAGOH/B Pool, a significant increase in GADD45A mRNA expression was observed in the cutaneous melanoma cell lines Mel Ho and 501Mel, whereas no obvious changes in the expression of GADD45B or GADD45G could be detected." (PMID 36497117, 2022).
cutaneous squamous cell carcinoma (1 paper, 2023).
diabetic cardiomyopathy (1 paper, 2022). Diabetic cardiomyopathy is a disorder of the heart muscle in people with diabetes. "For example, GADD45A was suggested as a diabetes-associated gene, which might be involved in both diabetic cardiomyopathy and DM-induced baroreflex dysfunction." (PMID 35213968, 2022).
diabetic foot ulcers (1 paper, 2023). "AGEs induced the demethylation of the MMP-9 promoter through the downregulation of GADD45a, which is involved in diabetic foot ulcers." (PMID 36866277, 2023).
dyslipidemia (1 paper, 2016).
Ebola hemorrhagic fever (1 paper, 2011). A viral hemorrhagic fever that is caused by the Ebola virus, which is transmitted by contact with infected animals or humans; it is characterized by high fever, unexplained bleeding, and a high mortality rate. "However, COX-2, GCH1, GM-CSF, MIP-3α, t-Pa, GADD45A, and IDO (6 h) are genes identified to play a role in Ebola hemorrhagic fever for the first time." (PMID 22028943, 2011).